CD47 (CD47 molecule)
Diseases named in the same sentence as CD47 in open-access papers (continued):
Sharing a sentence is not in itself a finding about the gene and the disease.
bladder cancer (continued). "Very few studies report the expression of CD47 in human clinical samples of bladder cancer." (PMID 37373873, 2023). "Their data suggest that the correlation between CD47 and SIRPα expression may play a key role in the progression of bladder cancer." (PMID 37373873, 2023). "Although some preliminary data suggest that bladder cancer shows increased expression of CD47, much remains unknown about its clinicopathologic significance in muscle invasive bladder cancer (MIBC) and its role in targeted therapeutic strategies." (PMID 37373873, 2023). "In vitro, blocking CD47 using monoclonal antibodies could induce macrophage phagocytosis in muscle invasive bladder cancer cells." (PMID 35903544, 2022). "CD47, a cell-surface protein that prevents cancer cell phagocytosis via the “don’t eat me” signaling, is highly expressed on several human cancers, including acute myeloid leukemia, non-Hodgkin’s lymphoma, and bladder cancer." (PMID 34064074, 2021). "It has also been reported that CD47 is expressed on more than 80% of the surface of bladder cancer cells, and that the expression of CD47 in muscular invasive bladder cancer (MIBC) and non-muscle invasive bladder cancer (NMIBC) is significantly higher than that in normal urothelial cells." (PMID 32082311, 2020). "Finally, novel imaging methods, including optical molecular imaging such as targeted antibodies for CD47 or pH low insertion peptides (pHLIPs), are being developed and assessed in bladder cancer." (PMID 30421080, 2019). "CD44 and CD47 are both supposed to be biomarkers of bladder cancer TICs." (PMID 25658794, 2015). "We further investigated CD47 expression levels in different tumor stages and grades and observed that CD47 is highly expressed in high-grade bladder cancer and muscle-invasive bladder cancer, which suggests that CD47 may be clinically associated with poor prognosis in bladder cancer." (PMID 39335665, 2024). "Our study assessed the anti-tumor efficacy of CD47 blockade in bladder cancer, indicating that CD47 is a suitable immunotherapy target for bladder cancer and CD47 blockade could inhibit the growth of bladder cancer through promoting the macrophage-mediated anti-tumor immunity." (PMID 39335665, 2024). "Thus, we performed in vitro phagocytosis assays to assess whether the phagocytosis of CD47-expressing bladder cancer cells by human macrophages could be restored after CD47 blockade with the SIRPα-Fc fusion protein." (PMID 39335665, 2024). "It remains unclear whether CD47 is a suitable target for bladder cancer." (PMID 39335665, 2024). "Therefore, we evaluated whether angiogenesis weakens the anti-tumor effect of CD47 blockade therapy in the bladder cancer CDX model." (PMID 39335665, 2024). "However, the therapeutic effect of blocking CD47 in bladder cancer remained unclear." (PMID 39335665, 2024). "Thus, we reasoned that the combination of anti-angiogenic drugs with CD47 blockade might provide a superior anti-tumor effect in bladder cancer." (PMID 39335665, 2024). "Moreover, blocking CD47 and angiogenesis could achieve a potent anti-tumor effect and could be an effective immunotherapy strategy for bladder cancer." (PMID 39335665, 2024). "In addition, CD47 was also considered a bladder cancer stem-cell marker." (PMID 35628262, 2022). "CD47 may be a target for bladder cancer immunotherapy and a BCSC marker." (PMID 35342431, 2022). "In this retrospective study of 87 patients with muscle invasion bladder cancer (MIBC), we examined CD47 IHC expressions in tumor samples from transurethral resections of bladder tumors (TURBT) and matched radical cystectomy (RC) specimens." (PMID 37373873, 2023). "Interestingly, CD47 overexpression is associated with negative clinical outcomes in lung and gastric cancers; however, the expression and functional significance of CD47 in bladder cancer is not fully understood." (PMID 37373873, 2023).
bladder cancer (continued). "Using indocyanine green (ICG) and anti-CD47, we synthesized a new ICG-anti-CD47 near-infrared (NIR) fluorescence probe for the diagnosis of bladder carcinoma in fresh human samples obtained through radical cystectomy." (PMID 36937442, 2023). "Bladder cancer stem cells have been described by expression of stem cell markers, among them CD24, CD44, and CD47, respectively." (PMID 35682984, 2022). "Targeting CD47 and angiogenesis could further promote macrophage-mediated anti-tumor immunity and effectively inhibit the growth of CDX bladder cancer." (PMID 39335665, 2024). "The transmembrane protein CD47 is overexpressed in bladder cancer cells but is absent in normal urothelium." (PMID 39606239, 2024). "CD47 expression is elevated in approximately 70% of bladder cancers, but is absent in normal urothelium." (PMID 35740662, 2022). "CD47-targeted NIR-PIT increased direct cancer cell death and phagocytosis, resulting in inhibited tumor growth and improved survival in a murine xenograft model of human bladder cancer." (PMID 34064074, 2021). "Histological tests for bladder cancer primary transplant nodules in nude mice showed that CD44 and CD47 were highly expressed in the outer rim of cells in tumor nodules, but most internal cells in the nodules are CD44-low and CD47-low." (PMID 25658794, 2015). "Notably, key pathways with significant effects on TAMs, such as CSF1-CSF1R axis, CCL2-CCR2 axis, and CD47-SIRPα axis, have very few or no clinical studies conducted in the context of bladder cancer." (PMID 39606239, 2024). "Blocking CD47 could enhance the human PBMC-derived macrophages’ phagocytosis of T24 (from 10.40% to 29.70%) and 5637 (from 5.31% to 33.52%) human bladder cancer cells, as well as demonstrate anti-tumor effects in the HSPCs-CDX model (tumor growth inhibition rate, TGI: 33.05%)." (PMID 39335665, 2024).
pancreatic cancer (45 papers, 2015 to 2025). "While CD47 has been a more well-established biomarker and negative predictor in hematologic malignancies, recent studies with breast and pancreatic cancer have also revealed an association between CD47 expression with HIF-1α." (PMID 33348579, 2020). "Dual targeting of this axis has shown promise in models such as pancreatic cancer models, in which combining CD47 inhibition with necroptosis inducers significantly curtailed metastasis." (PMID 41163221, 2025). "Mice with mouse pancreatic cancer cell line overexpressing miR-340 treated with an anti-CD47 developed a high presence of M1-macrophage and T cells, leading to increased tumor cell phagocytosis." (PMID 38339019, 2024). "Our unpublished data further showed excellent detection ability of [68Ga]Ga-NOTA-C2 and [89Zr]Zr-DFO-ABDC2 in pancreatic cancer with high expression of CD47." (PMID 36939440, 2023). "In conclusion, our findings show that the blockades of BAG3/BAG3R and SIRPα/CD47 axes converge in eliciting a sound anti-tumor immune response against pancreatic cancer and in countering tumor growth and the metastatic process." (PMID 35241649, 2022). "They proved the in vitro effectiveness of the preparation following administration in CD47-positive pancreatic cancer cells." (PMID 34360829, 2021). "Exosomal CD47 decreases pancreatic cancer cell clearance by phagocytes, while the relationship of exosomal CD47 with autophagy is still unclear." (PMID 34493296, 2021). "Suppressing CD47 using monoclonal antibodies has been exploited recently to treat pancreatic cancer." (PMID 34360829, 2021). "Previous studies have shown that CD47 expression tempers the phagocytosis of macrophages, but little is known about CD47 expression in fibroblasts and its implication in pancreatic cancer." (PMID 34745998, 2021). "Meaningful expression of the anti-phagocytosis signal CD47 has also been noticed in pancreatic cancer cells, mostly in cancer stem cells (CSCs), which are partly responsible for chemoresistance and for being aggressive." (PMID 34360829, 2021). "Another study using exosomes for the treatment of pancreatic cancer indicated the ability of CD47 positive exosomes to evade phagocytosis by circulating monocytes, increasing their half-life in circulation." (PMID 34829923, 2021). "Treatment with a CD47-blocking antibody also leads to delayed progression of metastasis and prolonged survival in mice with pancreatic tumors." (PMID 32082311, 2020). "Targeting CD47 efficiently enhanced phagocytosis of a representative set of primary human pancreatic cancer (stem) cells and, even more intriguingly, also directly induced their apoptosis in the absence of macrophages during long-term inhibition of CD47." (PMID 29156578, 2017). "Strategies based on CD47 blockade are also currently under development giving promising results in multiple pancreatic cancer preclinical models." (PMID 26046793, 2015). "Additionally, it would be worthwhile to evaluate the response of a pancreatic cancer model with high CDH17 expression in immunocompetent mice to bacteria‐mediated PTT combined with CD47 nanobody." (PMID 38888519, 2024). "Therefore, we further evaluated the effects of HT combined with anti-CD47 antibody on mouse pancreatic cancer progression, and our findings indicated that HT enhanced the anti-tumor effect of anti-CD47 antibody in vivo." (PMID 34858184, 2021). "Therefore, we further evaluated the effects of HT combined with anti-CD47 antibody on mouse pancreatic cancer progression." (PMID 34858184, 2021). "A previous study revealed that anti-CD47 CAR-T was effective in pancreatic cancer cells." (PMID 34189144, 2021). "The CD47 anti-phagocytic ligand is highly expressed in a majority of primary pancreatic cancer stem cells (CSCs) and targeting CD47 on PDAC cells demonstrated changes in the behavior of immunosuppressive resident tumor-associated macrophages (TAMs) to inhibit tumor growth instead." (PMID 32664564, 2020).
pancreatic cancer (continued). "In addition to its function as a ‘don't eat me’ signal, CD47 controls cell differentiation and the stress response, along with regulating the state of pancreatic cancer stem cells." (PMID 31899582, 2020). "Western blot and qRT-PCR confirmed that miR-128 could regulate ZEB1 and further inhibit CD47 in pancreatic cancer cells." (PMID 32536914, 2020). "GrA reduced the expression level of CD47 remarkably and disrupted functional clusters of CD47 in MIA PaCa-2 cell surface, which may cause those pancreatic cancer cells recognized and engulfed by macrophages." (PMID 31139022, 2019). "Notably, anti‐CD47 treatment may enhance anti‐tumor T‐cell immunity, and a recent publication on pancreatic cancer indicated that CD47 targeting induces remodeling of tumor‐infiltrating immune cells of the tumor microenvironment." (PMID 36598153, 2023). "Moreover, miR-128 regulates the infiltration of antitumor immune cells, including dendritic cells (DCs), CD8 + T cells, and NKT cells, in the immune microenvironment via the ZEB1/CD47 axis and epithelial-mesenchymal transition, ultimately inhibiting pancreatic cancer growth and metastasis." (PMID 34968167, 2022). "By simultaneously blocking CD47 and CD24 signaling, PAC-SABI enhances the phagocytic ability of macrophages in vitro and in vivo, promoting anti-tumor responses in breast and pancreatic cancer mouse models." (PMID 38971872, 2024). "In this report, we demonstrate the efficacy of CD47-CAR-T cells against several cancer cells: ovarian, lung, hepatocellular carcinoma and pancreatic cancer cell lines." (PMID 29065481, 2017). "Additionally, comprehensive analysis of pathological staining revealed that anti-CD47 nanobody therapy more effectively reduced the infiltration of F4/80+CD163+ TAMs and increased the infiltration of F4/80+CD86+ TAMs in pancreatic cancer with CCT6A knockdown." (PMID 40374617, 2025). "For example, CD47 has been identified as a do not eat me signal in lung and pancreatic cancers; CD47‐expressing lung and pancreatic CSCs escape phagocytosis of macrophages." (PMID 37576862, 2023). "In the pancreatic cancer microenvironment, two distinct mechanisms involved in supporting tumor growth and suppressing the anti-tumor immune response are mediated by BAG3/BAG3R and SIRPα/CD47 axes." (PMID 35241649, 2022). "The engineered exosomes (known as iExosomes) target oncogenic KRAS with enhanced efficacy probably due to that CD47 on exosomes surface contributed to the evasion from immune clearance in the circulation, and KRAS-stimulated macropinocytosis increased pancreatic cancer cells uptake of iExosomes." (PMID 29415727, 2018). "To test in vivo efficacy of CD47-CAR-T cells, we used BxPC3 pancreatic cancer cells." (PMID 29065481, 2017).
myelodysplastic syndrome (43 papers, 2016 to 2026). A clonal hematopoietic disorder characterized by dysplasia and ineffective hematopoiesis in one or more of the hematopoietic cell lines. "A phase I-b study combining Magrolimab, an anti-CD47, with azacitidine in patients with myelodysplastic syndromes or AML shows very promising results with a percentage objective response rate of 100% in MDS and 69% in AML." (PMID 37143666, 2023). "CSF1R inhibitor and anti-CD47 antibodies or anti-SIRPα antibodies have been applied for solid tumors and some hematologic malignancies such as acute myeloid leukemia and myelodysplastic syndrome (MDS)." (PMID 33644032, 2020). "In a phase I study, the lack of efficacy of CC-90002, an anti-CD47 antibody led to the discontinuation of the clinical trial that targeted patients with refractory or relapsed AML or high-risk myelodysplastic syndromes." (PMID 37143666, 2023). "In addition, activity has also been observed with anti-CD47 antibodies particularly in Myelodysplastic Syndrome (MDS)." (PMID 37638048, 2023). "The most advanced anti-CD47 mAb in development is Hu5F9-G4 (magrolimab), which the US Food and Drug Administration granted fast track designation for AML and myelodysplastic syndrome." (PMID 36439116, 2022). "In myelodysplastic syndrome (MDS), CD47 expression is high in high-risk patients compared to low-risk MDS and controls, indicating CD47 as a negative clinical prognosis marker." (PMID 34584838, 2021). "In the field of oncology, CD47 was first identified as a tumor antigen in human ovarian cancer and has since been found to be overexpressed in several malignancies, including non-Hodgkin’s lymphoma, T-cell lymphoma, AML and myelodysplastic syndrome (MDS)." (PMID 38638433, 2024). "In preclinical models of AML and myelodysplastic syndromes (MDS), it could be demonstrated that the blocking of CD47 enhances antitumor response and that the anti-CD47 antibodies stimulate ADCP, promoting priming and memory response of CD8 T cells." (PMID 35008269, 2021). "In addition, it has recently been reported that anti-CD47 mAb magrolimab was not superior relative to the standard of care (SOC) in two phase III trials in patients with high-risk myelodysplastic syndrome (HR-MDS) and AML when used in combination with the SOC." (PMID 38448430, 2024). "Blockade of CD47 leads to engulfment of leukemic cells, with preclinical studies demonstrating antimalignant activity in AML and myelodysplastic syndrome (MDS)." (PMID 34990402, 2022). "Although CD47 is widely expressed on the surface of a broad range of cell types, high levels of CD47 have also been observed in haematological cancers such as acute myeloid leukaemia (AML), ALL, CLL, multiple myeloma (MM), myelodysplastic syndrome (MDS), DLBCL, MCL, and MZL." (PMID 33430146, 2021). "Recently, two clinical trials evaluating anti-CD47 mAbs were terminated: CC-90002 in AML and myelodysplastic syndromes (MDS) and SRF231 in patients with advanced solid tumors and hematological cancers." (PMID 31801627, 2019). "Finally, the expression of CD47 has been studied in conditions that might evolve into AML, such as myelodysplastic syndrome (MDS), myeloproliferative disorders, and chronic myeloid leukemia (CML)." (PMID 34944878, 2021).
myeloma (41 papers, 2012 to 2026). "We additionally observed a frequent upregulation of CD47 in myeloma cells, an integrin-associated receptor protein that inhibits the phagocytosis of target cells." (PMID 34845188, 2021). "ISB 1442 thus represents a CD47-BsAb combining biparatopic targeting of a tumor associated antigen with engineered enhancement of antibody effector function to overcome potential resistance mechanisms that hamper treatment of myeloma with monospecific anti-CD38 antibodies." (PMID 38448430, 2024). "CD47 expression in myeloma cells also leads to immune evasion through its interaction with signal regulatory proteins on dendritic cells or macrophages." (PMID 38284882, 2024). "Recent studies have demonstrated the high expression of CD47 on malignancy PCs, further supporting CD47 as a potential immunotherapy target for multiple myeloma." (PMID 38783333, 2024). "In summary, we screened specific nanobodies against BCMA and CD47 protein from an immunized camel VHH library, and developed a novel allogeneic “off-the-shelf” BCMA/CD47-directed UCAR-T therapy for multiple myeloma." (PMID 38783333, 2024). "Study demonstrated that bortezomib-resistant multiple myeloma patient-derived xenograft is sensitive to anti-CD47 therapy." (PMID 39040441, 2024). "Delivery of CD47-SIRPα checkpoint blocker by BCMA-directed universal chimeric antigen receptor T (UCAR-T) cells enhances antitumor efficacy in multiple myeloma in the xenograft model." (PMID 39040441, 2024). "Myeloma cells have been shown to overexpress CD47 in a significantly larger amount compared to MGUS and SMM indicating a potential therapeutic target." (PMID 38322418, 2024). "Blocking CD47 with a CD47 mAb has been shown to increase phagocytosis of myeloma cells in vitro, and retard the growth of patient myeloma cells and alleviate bone resorption in human bone‐bearing mice." (PMID 37840445, 2023). "Clinical trials are currently conducted to test the efficacy of the anti-CD47 monoclonal antibody magrolimab in combination with other anti-myeloma drugs in relapsed and therapy refractory MM patients." (PMID 37744361, 2023). "In preclinical studies, CD47 blockade resulted in increased phagocytosis and reduced growth of CD47 expressing myeloma cell lines both in vitro and in vivo." (PMID 37744361, 2023). "CD47 is associated with the degree of immune deactivation, and the therapeutic strategy concerning anti-CD47 has been employed to kill myeloma (MM) cells." (PMID 35464451, 2022). "Myeloma cell lines were shown to display high levels of CD47 in a universal manner, similar to the levels observed in the primary patient samples." (PMID 32012878, 2020). "CD47 is also overexpressed on myeloma cells, and its expression increases with the progression of multiple melanoma (MM)." (PMID 32082311, 2020). "In their mice engrafted MM models, anti-CD47 Ab B6H12 inhibited the growth of myeloma cells and led to significant tumor regression and eradication, with a remission rate of 72% vs 19% in the control group at 6 weeks." (PMID 32677994, 2020). "In the other report, PI of human myeloma cells with mouse macrophages was about 50% when CD47 is present, but it increases to about 70% when CD47 was absent." (PMID 24927426, 2014). "Moreover, the upregulation of CD47 expression has been observed in multiple myeloma, and anti-CD47 antibodies have shown remarkable results in clinical trials." (PMID 38783333, 2024). "Clinical trials with CD47 inhibitors in myeloma area awaited." (PMID 38322418, 2024). "Targeting CD47 is under evaluation to eradicate myeloma-initiating cells." (PMID 36752202, 2023). "In multiple myeloma (MM), transition from the precursor disease monoclonal gammopathy of undetermined significance (MGUS) to MM is associated with a significant increase in the population of plasma cells expressing CD47." (PMID 34584838, 2021). "One study found that 73% of MM patients had overexpression of CD47 compared to non-myeloma cells." (PMID 34584838, 2021).